RPLP0P2 (ribosomal protein lateral stalk subunit P0 pseudogene 2 )
Synonyms: RPLP0L2; RPLP0_3_1146
Gene: Long non-coding RNA gene on chromosome 11 (61,614,987 to 61,639,449, forward strand). Ensembl gene ENSG00000293352.
Diseases named in the same sentence as RPLP0P2 in open-access papers:
RPLP0P2 is named in the same sentence as 5 diseases in open-access papers, as found by Europe PMC text mining. Sharing a sentence is not in itself a finding about the gene and the disease. The quoted sentences say what the papers report.
colorectal cancer (2 papers, 2021 to 2025). A primary or metastatic malignant neoplasm that affects the colon or rectum. "RPLP0P2 is a pseudogene associated with a variety of cancers including lung adenocarcinoma and colorectal cancer." (PMID 34966413, 2021). "The ceRNA network involving RPLP0P2 has been shown to regulate mRNA expression by interacting with 15 specific miRNAs, highlighting the crucial role of non‐coding RNAs in colorectal cancer progression, diagnosis, and treatment." (PMID 40556338, 2025).
lung adenocarcinoma (2 papers, 2014 to 2021). A carcinoma that arises from the lung and is characterized by the presence of malignant glandular epithelial cells. "Among these, LOC100132354 and RPLP0P2 were the most aberrantly expressed lncRNAs, as estimated by quantitative PCR in 100 pairs of lung adenocarcinoma and NT samples." (PMID 25089627, 2014). "Of these, LOC100132354 and RPLP0P2 exhibited the most significantly changed expression in our analysis of 100 pairs of lung adenocarcinoma and normal lung tissue samples." (PMID 25089627, 2014). "The expression of LOC100132354 was significantly higher in lung adenocarcinoma than in the adjacent tissues (Mann-Whitney U = 126.00, P = 0.01), while the expression of RPLP0P2 was significantly lower in lung adenocarcinoma than in the adjacent tissues (Mann-Whitney U = 178.78, P = 0.002)." (PMID 25089627, 2014). "Moreover, we found that LOC100132354 and RPLP0P2 might contribute to the development of lung adenocarcinoma." (PMID 25089627, 2014).
lung carcinoma (1 paper, 2017). "In network, 4 pseudogenes (RRP7B, RPLP0P2, MSTO2P and AFG3L1P) co-methylated with EZH2, suggesting an involvement in the progression of lung cancer." (PMID 28938616, 2017).
cancer (3 papers, 2019 to 2025). A tumor composed of atypical neoplastic, often pleomorphic cells that invade other tissues. "Additionally, other ceRNAs within the network, including the pseudogene RPLP0P2, were identified as potential contributors to cancer progression by modulating mRNA expression levels through miRNA binding." (PMID 40556338, 2025). "Other ceRNAs like H19 in the network, such as pseudogene RPLP0P2, may also play a pivotal role in cancer progression by regulating the expression level of mRNAs through sponging various miRNA." (PMID 31164794, 2019).
tumor (3 papers, 2017 to 2025). "Several studies have shown that low expression of RPLP0P2 can lead to decreased proliferation and adhesion of tumor cells." (PMID 34966413, 2021). "In addition, RPLP0P2 was proved to be associated with cell proliferation and adhesion in LUAD tumor cells." (PMID 28938616, 2017). "Downregulating RPLP0P2 inhibits CRC cell viability, migration, and invasion, alters EMT markers, and suppresses tumor growth in vivo." (PMID 40556338, 2025). "miR‐129‐5p targets ZBTB20, and its inhibition reverses the effects of RPLP0P2 downregulation, while ZBTB20 overexpression counteracts miR‐129‐5p's tumor suppression." (PMID 40556338, 2025). "RPLP0P2 is upregulated in CRC and promotes tumor progression by sponging miR‐129‐5p." (PMID 40556338, 2025).